MYBL2 (MYB proto-oncogene like 2)
Diseases named in the same sentence as MYBL2 in open-access papers (continued):
Sharing a sentence is not in itself a finding about the gene and the disease.
tumor (continued). "Taken together, the data from the tumor xenografts support that E2F1 and E2F7 transcriptionally activate and repress MYBL2 to promote and inhibit GC cell proliferation, respectively." (PMID 39613162, 2024). "CDK2 is a transcriptional target of MYBL2, which holds true in both NE-like murine tumor models, in which a significant reduction in CDK2 expression occurred in tumors with MYBL2 KO." (PMID 39113611, 2024). "Kaplan‒Meier tumor-free curves showed that although the MYBL2-knockdown group presented the latest tumor onset, the mice with E2F1 overexpression and MYBL2 knockdown appeared to have later tumor onset than those with E2F1 overexpression alone." (PMID 39613162, 2024). "In this study, MYBL2 transcriptionally activated CCL2 and further promoted the recruitment and M2-like polarization of macrophages, thereby inducing tumor progression and anti-PD-1 therapy tolerance." (PMID 37865750, 2023). "Across these tumor types, patients with MYBL2 High disease had significantly worse OS, disease-specific survival (DSS), and PFS outcomes compared to MYBL2 Low patients." (PMID 36358918, 2022). "Unexpectedly, the correlation analysis between the upstream regulator's analysis identified MYBL2, E2F2, CBX3, FOXM1, and E2F1, which were significantly elevated in the LUAD or LIHC tumor groups, with a strongly correlated value with utility as biomarkers." (PMID 35404841, 2022). "The expression of MKI67, MYBL2 and CCNB1 was significantly correlated with miR-200c-3p expression, both in pre- and post-NCT tumor samples." (PMID 35625994, 2022). "In vivo analysis using xenograft tumors also revealed MYBL2 regulated purine synthesis by regulating IMPDH1, and thus, influencing tumor progression." (PMID 36494680, 2022). "Some of them have been reported to play important roles in the development of tumor proliferation, apoptosis, and metastasis, such as IGF1R, MYBL2, POLE, and DDAH1." (PMID 32923489, 2020). "MYBL2 is known to promote cell proliferation and EMT in many tumor types, and TOP2A is associated with worse prognosis in non‐small‐cell lung cancer patients." (PMID 30913346, 2019). "High levels of expression of this transcription factor in other tumor types may reflect the greater proliferative rate of the tumor cell population compared to resting cells, so that the apparently levels of high MYBL2 activity may be a consequence rather than a cause of malignant transformation." (PMID 23878725, 2013). "In the yellow cluster, cell cycle regulators such as CCNE2, MYBL2, and MCM4 were strongly suppressed in the combination, confirming that this approach induced cell cycle arrest and exerted a stronger inhibition of tumor cell proliferation compared to either treatment alone." (PMID 40753072, 2025). "Upon comparison of the tumor tissue with the adjacent tissue, increased expression of MYBL2 was noted in the tumor tissue, potentially contributing to the lack of improvement in extramedullary relapse after dual-targeted CAR-T cell therapy." (PMID 39139556, 2024). "CDK2 activated MYBL2 by phosphorylation, leading to anti-PD-1 resistance in OC, but the CDK2 inhibitor CVT-313 suppressed MYBL2 in A2780 and SKOV3 OC cells and circumvented anti-PD-1 resistance of murine ID8 OC by modulation of the tumor microenvironment." (PMID 38835346, 2024). "The parent cell line, SUIT-2, originated from metastasis, while many other cells in which MYBL2 knockout was studied were derived from primary tumours or non-cancerous tissues." (PMID 39518122, 2024).
tumor (continued). "Genes such as MYBL2, TOP2A, and MMP1 were significantly upregulated in tumor tissues." (PMID 38124743, 2023). "This study showed that tumor-derived MYBL2 transcriptionally activated CCL2 and recruited M2-like macrophages within clinical tumor tissues and model mice, and thus structured the immunosuppressive OVC microenvironment and attenuated the response to anti-PD-1 therapy." (PMID 37865750, 2023). "Furthermore, using a combination of metabolomics and genomic analysis, we demonstrate that MYBL2 promotes de novo purine anabolism by up-regulating IMPDH1 at transcriptional level, facilitating tumor growth in vivo." (PMID 36494680, 2022). "It is interesting that, the expressions of MYBL2, CSE1L, and most neighbors of NAE1 (59/63) are significantly different between tumor and normal tissues (P-value < 0.05, Wilcoxon rank sum test with continuity correction), but as a link gene NAE1 is not differentially expressed." (PMID 36266635, 2022). "In addition, our results show that MYBL2 and MYBL1 genes are also involved in the activation of the EMT pathway to promote tumor metastasis, which has also been confirmed in some tumors." (PMID 35664326, 2022). "While we find that MYBL2 expression robustly identifies patients with poor outcomes across tissue types, it should be noted that MYBL2 expression as a single marker did not stratify all known tumor types." (PMID 36358918, 2022). "We then quantified to what extent the negative expression correlation between KDM5D and MYBL2 observed in vitro was reflected as an inverse association of KDM5D and MYBL2 in tumor tissue from patients." (PMID 36087093, 2022). "When enhancing the adhesion ability of the extracellular matrix (including laminin, collagen, and fibronectin), TF MYBL2 is upregulated to promote the activity of epithelial–mesenchymal transition (EMT), enabling tumor cells to acquire the characteristics of migration and invasion." (PMID 35164166, 2022). "However, the staining intensity or the range of positive areas of CEP55, KIF23, MYBL2, and RACGAP1 was higher in tumor samples (medium or high levels) than in non-tumor tissue." (PMID 34093635, 2021). "In addition to these genes that directly regulate tumor-microenvironment and desmoplasia, the top targets identified from our dataset consisted of the two additional genes E2F7 and MYBL2, which play essential roles in cell cycle regulation." (PMID 32660466, 2020). "Together, this data confirmed that MYBL2 expression is an important prognostic variable for both OS and DFS patient outcomes, after adjusting for other key clinical factors such as age at diagnosis, tumor (T) stage, and patient smoking history." (PMID 33489883, 2020). "In both cell lines, DOX-induced MYBL2 silencing significantly reduced clonogenic growth in vitro and tumor growth in vivo compared to a non-targeting control shRNA." (PMID 31511524, 2019). "Six genes (including genes encoding ER, PR, HER2 and their transcription factors MYC, FOXA1, MYBL2) were removed from PAM50 (the new panel is named PAM50–6) to exclude their confounding effect on the classifier, as the ground truth was based on tumor classification stratified by ER, PR and HER2." (PMID 31699026, 2019). "In addition, many studies have reported that hsa-miR-30a-5p is a tumor suppressor in GC, and recent studies have shown that CCNA2, MYBL2, DTL, and STMN1 are regulated by hsa-miR-30a-5p." (PMID 29912172, 2018). "As expected, we found that gene expression patterns are different in PC tumor samples compared to normal, undiseased peritoneum with a number of genes differentially regulated: BAG1, CCNB1, CD44, CLDN4 and 6, MMP2, MKI67, MUC1, MYBL2, and SERPINB3." (PMID 27542596, 2016).
tumor (continued). "Similarly, in the older patients, ANGPTL4, MYBL2 and VEGFA, all maintained significance after correcting for subtype and tumor grade in multivariate analysis (Multivariate Model)." (PMID 25999348, 2015). "The expected model size with the highest performance level consists of 10 of the most robust predictive variables and is comprised of four clinico-pathological variables and six additional proteins: nodal status, tumor size, AURKA, BCL2, age, CD68, HER2, MYBL2, CCNB1 and GSTM1." (PMID 20809974, 2010). "Screening tumor samples for AURKA, TPX2, and MYBL2 expression is feasible, and could be incorporated into design of clinical trials for Kinesin-5i response." (PMID 19259408, 2008). "Mechanistically, miR-29a was shown to suppress MYBL2 translation by directly binding to its 3'-UTR; this was validated in vivo, where miR-29a transgenic mice were protected from WD/CCl4-induced HCC, demonstrating reduced tumor burden, MYBL2 expression, and fibrosis." (PMID 42065054, 2026). "Similarly, MYBL2 promotes cell cycle progression by transactivating targets, such as CDCA3, and interacting with FOXM1 to potentiate Wnt signaling, thereby further promoting tumor progression." (PMID 41439026, 2025). "However, the group with MYBL2 inhibition that received anti-PD-1 therapy showed significantly reduced tumor volume compared to the group without anti-PD-1 therapy." (PMID 37865750, 2023). "For example, miR-655 may suppress the proliferation of PCa cells and tumor metastasis by inhibiting TRIM24 and miR-30a may inhibit the androgen-independent growth of PCa cells by targeting the expression levels of MYBL2, FOXD1, and SOX4." (PMID 35782093, 2022). "It was predicted that the genes such as FOXM1 and MYBL2 were activated while HNF4A and PPARGC1A were inhibited in tumor cells, which drove liver tumor, digestive organ tumor, abdominal neoplasm, tumorigenesis of tissue, neoplasia of cells and oxidation of lipid." (PMID 36212481, 2022). "Indeed, the MYB family proteins are widely distributed in eukaryotic organisms and expresison of MYB-transcription factor is critical for tumor growth and mammary carcinogenesis, while MYBL2 (B-MYB) is an oncogenic transcription factor involved in cell cycle, G2/M progression." (PMID 25860484, 2015). "Hence, MYBL2 appears to be expressed at reduced levels in nearly two-thirds of MDS cases, including those with a normal karyotype, suggesting that it functions as a dose-dependent tumor suppressor gene." (PMID 23878725, 2013). "MYBL2 High tumors, regardless of tumor type, exhibited significantly elevated combined HRD scores and decreased RPS scores, compared to MYBL2 Low tumors." (PMID 36358918, 2022).
infection (4 papers, 2013 to 2023). The state of being infected such as from the introduction of a foreign agent such as serum, vaccine, antigenic substance or organism. "In the healed group (n = 17), RRM2 and MYBL2 were significantly upregulated during active infection at 0 weeks but became downregulated at 8 weeks following therapy (p = 3.61E-07 and 2.7E-06 with corresponding FDR values of 0.001994 and 0.006835, respectively)." (PMID 37434783, 2023). "We noted a high level expression of RRM2, MYBL2, and some other genes such as GALNT14, CENPU, ACOXL, and U2 at 0 weeks during active phase of infection, which were downregulated at 8 weeks after therapy." (PMID 37434783, 2023). "Parallel to upregulation of core histones, the CD177 gene (a neutrophil-specific marker), MYBL2 and RRM2 were highly expressed during the active phase of infection (0 weeks) and the expressed genes were reduced at 8 weeks after therapy." (PMID 37434783, 2023). "Of the top 10 transcripts upregulated at peak HIV-1 viral load, the majority (6 out of 10) were related to cell cycle and cell division including RRM2, MYBL2, CDK1, UBE2C, CDC45, and TK1 with 8 to 15-fold increased expression compared to the pre-infection samples." (PMID 31937782, 2020).
adenocarcinoma (2 papers, 2018 to 2024). A common cancer characterized by the presence of malignant glandular cells. "Of interest, a subset of samples from patient with CRPC (adenocarcinoma) did exhibit medium-to-high levels of MYBL2; however, overall MYBL2 expression was significantly increased in NEPC samples." (PMID 39113611, 2024). "Gene expression analysis further supported this by indicating that Mybl2 mediated transcriptional programs related to self-renewal and pluripotency, as well as increased stem cell signatures in samples from patients with NEPC and patients with adenocarcinoma with highest MYBL2 expression." (PMID 39113611, 2024). "Moreover, we observed that MYBL2 transcriptional activity was most positively correlated in murine and human with NE and embryonic stem cell (ESC) gene signatures in NEPC samples versus adenocarcinoma." (PMID 39113611, 2024).
hematologic disorder (2 papers, 2013 to 2023). A disease involving the hematopoietic system. "MYBL2 is essential to establish definitive hematopoiesis because mice with low levels of MYBL2 developed hematologic disorders during aging." (PMID 37865750, 2023). "Thus, our secondary transplantation assays show that either spleen or bone marrow cells from mice with myeloid neoplasia due to shRNA-mediated reduced Mybl2 expression can efficiently transmit the blood disorder to secondary recipients." (PMID 23878725, 2013).
MYBL2 also shares sentences with these, for which no sentence is quoted: non-small cell lung carcinoma (8 papers); triple-negative breast carcinoma (4); embryonic carcinoma (3); renal cell carcinoma (3); cervical squamous cell carcinoma (2); colorectal tumor (2); esophageal cancer (2); lung squamous cell carcinoma (2); rectum adenocarcinoma (2); acute lymphoblastic leukemia (1); adrenocortical carcinoma (1); asthma (1); bacterial vaginosis (1); Barrett adenocarcinoma (1); bladder urothelial carcinoma (1); borderline ovarian surface epithelial-stromal tumor (1); brain cancer (1); Burkitt lymphoma (1); Cervical Glandular Intraepithelial Neoplasia (1); CNS tumors (1); colon adenocarcinoma (1); digestive system carcinoma (1); endocervical adenocarcinoma (1); fibrosarcoma (1); inflammatory bowel disease (1); intestinal tumors (1); kidney disease (1); low grade glioma (1); lymphoma (1); mesothelioma (1).
A further 17 diseases each share a sentence with MYBL2 in 1 paper.